DCT (dopachrome tautomerase)
Description:
Plays a role in melanin biosynthesis. Catalyzes the conversion of L-dopachrome into 5,6-dihydroxyindole-2-carboxylic acid (DHICA).
Synonyms: TRP-2; TRP2; TYRP2; OCA8
Tractability: Small molecule: it belongs to a druggable protein family. Antibody: its Gene Ontology location is reachable by antibodies, with high confidence; UniProt predicts a signal peptide or a membrane-spanning region; the Human Protein Atlas places it where antibodies can reach.
Gene: Protein-coding gene on chromosome 13 (94,436,811 to 94,479,682, reverse strand). Ensembl gene ENSG00000080166.
Subcellular location: Melanosome membrane; Melanosome
Subcellular location (Human Protein Atlas): Plasma membrane; Vesicles
Pathways (Reactome):
Developmental Biology: Regulation of MITF-M-dependent genes involved in pigmentation
Metabolism: Melanin biosynthesis
Gene Ontology:
Molecular function: protein binding; copper ion binding; dopachrome isomerase activity; oxidoreductase activity
Biological process: response to blue light; developmental pigmentation; epidermis development; melanin biosynthetic process from tyrosine; positive regulation of neuroblast proliferation; ventricular zone neuroblast division; eye pigmentation; melanin biosynthetic process
Cellular component: plasma membrane; cytosol; melanosome; melanosome membrane; membrane; cytoplasm
Genetic constraint (gnomAD): Loss-of-function variants: 44 observed, 51.37 expected, observed/expected ratio (o/e) 0.86, 90% interval 0.67 to 1.1. The upper end of that interval is the gene's LOEUF score, 1.1, which puts it in group 4 of 6, group 1 being the genes least tolerant of losing a copy. Missense variants: 622 observed, 621.93 expected, observed/expected ratio (o/e) 1, 90% interval 0.94 to 1.07. Synonymous variants: 230 observed, 234.2 expected, observed/expected ratio (o/e) 0.98, 90% interval 0.88 to 1.1.
Homologues: Orthologues: chimpanzee DCT (99% identical), macaque DCT (96% identical), pig DCT (87% identical), dog DCT (85% identical), rabbit DCT (84% identical), guinea pig DCT (84% identical), mouse Dct (83% identical), rat Dct (82% identical), tropical clawed frog dct (68% identical), zebrafish dct (62% identical), Caenorhabditis elegans tyr-4 (17% identical), Caenorhabditis elegans F54E4.4 (7% identical). Paralogues in human: TYRP1 (49% identical), TYR (39% identical).
Diseases named in the same sentence as DCT in open-access papers:
DCT is named in the same sentence as 37 diseases in open-access papers, as found by Europe PMC text mining. Sharing a sentence is not in itself a finding about the gene and the disease. The quoted sentences say what the papers report.
melanoma (192 papers, 2006 to 2025). A malignant, usually aggressive tumor composed of atypical, neoplastic melanocytes. "For CD63 and PMEL, the GO term GO:0006583 (melanin biosynthetic process) and its associated genes TYR and DCT were positively associated, suggesting activation of the tyrosine-to-melanin conversion pathway in the Melanoma-A region." (PMID 41279463, 2025). "We used a replication-deficient adenovirus serotype 5-vectored cancer vaccine targeting the melanoma-associated antigen dopachrome tautomerase." (PMID 28814733, 2017). "Additionally, DCT is expressed by most melanoma cells, and it has been used as a melanoma differentiation antigen in diagnostic histopathology." (PMID 37628992, 2023). "However, DCT is also a marker for melanoma and the observed results for this gene may be caused by the melanoma cell lines all belonging to the sensitive cell line category." (PMID 21314952, 2011). "The first panel highlights melanoma-associated genes, including MITF, AXL, NGFR, TYRP1, and DCT, which are involved in the regulation of melanoma cell identity, dedifferentiation, and invasive potential." (PMID 40909289, 2025). "Pearl regulated microphthalmia‐associated transcription factors through CREB and affected melasma‐related genes TYR and DCT, which in turn inhibit melanoma cell activity and intracellular tyrosinase activity." (PMID 40369904, 2025). "The anti-melanogenic effects of B. alba were mediated through the inhibition of the regulator gene MITF and the downregulation of pigmentary genes, such as TYR, TRP-1, and DCT, in the human melanoma cells exposed to cAMP stimulator IBMX." (PMID 39335872, 2024). "The protein expressions of TYR, TRP-1 and DCT in MNT-1 melanoma cells were detected by Western-blot assays." (PMID 37108635, 2023). "Cell experiments and pan-cancer studies have shown that primary melanoma, metastatic melanoma, and nevus occur when DCT is overexpressed, and squamous cell carcinoma occurs when DCT is expressed at a low level." (PMID 35096060, 2022). "Gene signatures from group 2 corresponded to a proliferative and differentiated phenotype of melanoma (DCT, MLANA, TYR)." (PMID 35053440, 2022). "We also examined the transcription of melanin synthesis genes TYR, TYRP1, PMEL, MLANA and DCT by RNAseq analysis in M14 human melanoma cells in which we have disrupted TXNRD1 using Crispr/Cas9 (M14TXNRD1+/− cells)." (PMID 36291795, 2022). "Specifically, we performed immunohistochemical staining for the melanocyte and melanoma-specific marker DCT to identify metastatic lesions." (PMID 35693944, 2022). "In melanoma cells, β-catenin activates proteins involved in melanogenesis and pigmentation such Melan-A, dopachrome tautomerase (DCT) and tyrosinase, all through MITF." (PMID 34356645, 2021). "L-Cysteinamide inhibited TYR-mediated dopachrome formation in vitro and eumelanin synthesis without altering the mRNA and protein expression levels of TYR, TYRP1, and DCT in darkly pigmented human melanoma MNT-1 cells and/or normal HEMs." (PMID 34439449, 2021). "Trp2, an enzyme involved in melanin biosynthesis encoded by the dopachrome tautomerase (Dct) gene, is normally expressed by melanocytes in the skin in both humans and C57BL/6 mice and is overexpressed by many melanomas." (PMID 33929324, 2021). "In another study, 17-AAG increased expression of DCT (dopachrome tautomerase) and TYRP1 (tyrosinase-related protein 1) encoding pigmentation-related proteins, and elevated melanin production in melanoma cells." (PMID 31659567, 2020). "Boosting with Maraba virus expressing the human melanoma antigen dopachrome tautomerase (DCT) generated robust tumor-specific CD8+ T cell responses resulting in improved tumor control and unique immunological changes in tumors." (PMID 32698494, 2020). "BRAF inhibition is associated with increased melanoma antigen expression, including Melan-A and TYRP2 (DCT)." (PMID 31354817, 2019).
melanoma (continued). "Genetic silencing or chemical inhibition of NAT10 resulted in diminished melanin synthesis through the suppression of melanogenesis-stimulating genes such as those encoding dopachrome tautomerase (DCT) and tyrosinase in B16F10 melanoma cells." (PMID 28880216, 2017). "This was demonstrated in a murine B16 melanoma model that expresses the dopachrome tautomerase (DCT), a melanocyte-differentiation antigen." (PMID 28536388, 2016). "B16 cells express the TAA, dopachrome tautomerase (DCT), which is a protein involved in melanogenesis and is present in normal melanocytes and melanoma." (PMID 25161958, 2014). "A link between grm1 overexpression and the development of hereditary melanoma was demonstrated by the targeted expression of murine grm1 cDNA under a melanocyte-specific promotor (dopachrome tautomerase; DCT)." (PMID 22674057, 2012). "Genes with significantly decreased expression from baseline included at least one known melanoma antigen: tyrosinase-related protein-2 (DCT)." (PMID 22123319, 2011). "This study showed that PE may target CREB1 and thus regulate the MITF/TYR/DCT axis to reduce melanoma cell viability and the production of melanin." (PMID 40369904, 2025). "Importantly, the pigmentation markers Tyrosinase and DCT were reduced, both at protein and mRNA level, in human melanoma cell lines Mel JuSo, IPC-298 and SK-MEL-3 following downregulation of TG2 by siRNA." (PMID 37898636, 2023). "We used tumor tissue derived from the tails of Tg(Grm1)EPv mice, a melanoma mouse model derived from C57BL/6 mice that carries a metabotropic glutamate receptor 1 (Grm1) transgene under the control of the dopachrome tautomerase promoter, resulting in melanocyte-specific overexpression." (PMID 36831408, 2023). "The tumorigenic effects of SETDB1 are attributed to the regulation of Thrombospondin 1 (THBS1), which promotes melanoma invasiveness and metastasis as well as downregulation of the expression of DOPAchrome tautomerase (DCT), an enzyme that participates in melanin synthesis." (PMID 34440561, 2021). "MITF level and expression of MITF-dependent pigmentation-related genes, MLANA, PMEL, TYR, and DCT, in drug-naïve and vemurafenib- or trametinib-treated patient-derived melanoma cell lines and their drug-resistant counterparts were analysed and referred to genomic alterations." (PMID 31354817, 2019). "We next evaluated the impact of MCs on the expression of melanoma-specific genes: DCT and GP100." (PMID 31506436, 2019). "Here the 17-AAG dependent, tyrosinase-independent induction of melanin formation in human SK-Mel-30 melanoma cells implicates DCT and TYRP1 in facultative melanization, showing that these accessory melanogenic enzymes can modulate pigmentation without changes in tyrosinase." (PMID 29481571, 2018). "For instance, DCT is also a marker for melanoma and is melanocyte specific." (PMID 21314952, 2011). "To evaluate tumor type, we examined melanoma markers including DCT and S100 in all tumors." (PMID 21203491, 2010). "In addition, other pigmentation markers including TYR and DCT serve as melanoma antigens." (PMID 32978520, 2020). "In murine B16-F10 melanoma models, including lung metastases and intracranial tumors, MG1 engineered to express human dopachrome tautomerase (MG1-hDCT) effectively infected and killed tumor cells and preferentially replicated in tumor-bearing tissues." (PMID 41294689, 2025). "Further, we detected signature melanosomal markers TYR, DCT, GPR143, and GPNMB in the melanosomes derived from melanoma cells, fibroblasts and keratinocytes (Fig. EV2I)." (PMID 38719996, 2024). "HLA peptides from MDAs, such as DCT, PMEL and tyrosinase were recurrently detected exclusively in melanoma and melanocytes." (PMID 39835134, 2024). "As expected, TNF decreased the gene expression of MITF and its target genes MLANA, DCT and TYR, and, conversely, increased the expression of the stemness factor NGFR in 451Lu melanoma cells." (PMID 39136013, 2024).
melanoma (continued). "MITF has been extensively studied in melanoma cells where its transcriptional activity modulates target genes involved in pigmentation, such as TYR, MC1R, DCT, and MLANA." (PMID 37898636, 2023). "This transcription factor that promotes the expression of the most melanogenic proteins including TYR, TYRP1, DCT and PMEL, was found to be also critical for melanoma invasion and proliferation upon down-regulation in melanoma cells." (PMID 36776379, 2022). "We treated SB-3123p melanoma cells with either JQ1, BI-2536, Fenobam or PHA-793887 and found that the 4 compounds up-regulated the transcription of MITF and its target genes, DCT, Tyrp, Melan A and Pmel-1 in a dose dependent fashion as determined by qPCR." (PMID 32231230, 2020). "Next, we tested if the 36 active compounds from the IFNγ HTRF assay and the cell viability assay can affect expression of genes that regulate melanoma cells differentiation and pigmentation such as MITF, DCT, Melan-A and Tyrosinase-related protein 1(Tyrp)." (PMID 32231230, 2020). "Very low and enhanced levels of DCT expression in drug-treated MITF-Mlow and MITF-Mhigh melanoma cells, respectively, were also confirmed at the protein level by immunoblotting." (PMID 31354817, 2019). "Dopachrome tautomerase (DCT), the melanogenic enzyme is known for its overexpression in human melanoma cells that are resistant to both chemotherapy and radiation therapy." (PMID 31100919, 2019). "MET expression together with dopachrome tautomerase (TYRP2), which is part of the melanin synthesis process, is part of a melanoma signature and prognostic for tumor progression." (PMID 30823658, 2019). "Here, in addition, we describe a novel activity of the HSP90 inhibitor 17-AAG which induces melanization in BRAFWT melanoma cells in a tyrosinase-independent manner while increasing expression of accessory melanogenic enzymes and tumor antigens TYRP1 and DCT." (PMID 29481571, 2018). "Immunofluorescence experiments in mouse melanoma cells have showed strong colocalization of DCT and trans-golgi network (TGN) and limited colocalization of DCT with plasma membrane." (PMID 28095444, 2017). "DCT overexpression has been shown to reduce cellular sensitivity to oxidative stress and protect the DNA from oxidative stress damage in WM35 melanomas." (PMID 28095444, 2017). "MITF and its target genes are known to decrease as melanomas gain invasive capacity, and we observed an increase in ILEI along with a decrease in DCT." (PMID 28545079, 2017). "Among 142 upregulated genes in melanoma, many are known to be expressed specifically in melanocytes, including KIT, Melan-A, TYR, TRPM1, EDNRB, DCT, SOX10 and SILV." (PMID 21294715, 2011). "Moreover, both extracts demonstrated potential for inhibiting melanin production and intracellular tyrosinase activity in human melanoma cells by decreasing the expression of the transcription factor MITF and the pigmentary genes TYR, TRP-1, and DCT." (PMID 38999635, 2024). "Along with the results observed in B16 mouse melanoma cells, the relative gene expression levels of MITF, TYR, TRP-1, and DCT, after exposure to IBMX treatment, were significantly upregulated to 1.65 ± 0.12, 1.73 ± 0.15, 1.53 ± 0.12, and 1.67 ± 0.13, respectively, compared to the control group." (PMID 39684912, 2024). "The DCT gene is highly expressed in chemo- and radiotherapy-resistant mouse/human melanoma cells that undergo de-differentiation and thus can be used as a marker in complement of GP100 for melanoma detection and staging." (PMID 36497393, 2022). "Melanoma is a highly malignant tumor derived from melanocytes, which differentiate via melanogenesis regulated by melanocortin 1 receptor (MC1R), tyrosinase (TYR), TYR-related protein-1 (TYRP1), and dopachrome tautomerase (DCT)." (PMID 35619714, 2022).
melanoma (continued). "Indeed, we found a significant time-dependent Cpd1-induced transcription of the melanocytic master regulator MITF and other downstream differentiation genes like DCT, TYR, and MART-1/MLANA in pigmentation-competent melanoma cells." (PMID 35650266, 2022). "Then, we showed that adenovirus-forced MITF expression led to an increase in FBXO32 protein expression in both 501MEL and A375 melanoma cell lines, while MITF silencing decreased the expression of FBOX32 and DCT, a known transcriptional target of MITF in MeWo and 501Mel cell lines." (PMID 33462405, 2021). "In addition to MITF, other melanocytic genes (such as TYR, DCT, MART-1) are also upregulated in the proliferative phenotype of melanomas." (PMID 34698090, 2021). "We did not detect transcripts for melanoma antigens, gp100, Dopachrome tautomerase (DCT), Tyrosinase (Tyr), Melan-A and detected low levels of expression of Melanocyte Inducing Transcription Factor (MITF) in SB-3123p cells." (PMID 32231230, 2020). "Choosing SCM as the microenvironment for melanoma cells was crucial with transcriptomic analysis that serum present in the medium drastically reduces expression of MITF-M and 74 MITF-dependent genes, including TYR, DCT, and MLANA." (PMID 31354817, 2019). "Since we observed a close correlation between the Wnt3a-CM or PKF115–584 treatment and the expression of pigmentation related genes (DCT, TYR, TYRP1, MITF) in our SKMEL28 microarray data, we analyzed the TCGA melanoma RNAseq expression data concerning MLANA expression." (PMID 29454361, 2018). "Moreover, the lack in our lists of melanosome markers, such as DCT and GPNMB, excluded any possible contamination with melanosomes, known to be abundantly secreted from melanoma cells." (PMID 30290833, 2018). "In previous studies, DCT and TYRP1 were identified as melanoma tumor antigens." (PMID 29481571, 2018). "Surprisingly, 17-AAG also stimulated melanin production in SK-Mel-30 cells and enhanced TYRP1 and DCT expression without stimulating TYR production in all three BRAFWT cell lines studied as well as in B16F10 mouse melanoma cells." (PMID 29481571, 2018). "The prior identification of DCT and TYRP1 as melanoma tumor antigens prompted us to investigate whether melanoma cells became more immunogenic following 17-AAG exposure." (PMID 29481571, 2018). "Due to the high stringency of our search, ESTs for genes traditionally known as melanocyte/melanoma-specific genes, such as TYR (Hs.503555), DCT (Hs.301865), MLANA (Hs.154069), and SILV (Hs.95972), were not selected because they also match entries of other tissue datasets." (PMID 20975957, 2010). "To investigate this, we classified melanoma cell lines as either EP300/SOX10 co-amplified (>2 copies of both EP300/SOX10) or not co-amplified, treated them with the potent and specific p300 KAT inhibitor A-485, and probed for SOX10 and downstream SOX10 target genes, such as MITF and DCT." (PMID 38994683, 2024). "Additionally, we reported a GH-induced upregulation and GHRKD-induced suppression of MITF-regulated melanogenesis pathway genes—TYR, TYRP1, TYRP2/DCT—as well as melanosomal markers PMEL (gp100) and MLANA, in multiple melanoma cell lines, xenograft models, and in silico analyses." (PMID 31547367, 2019). "The non-immune cell clusters were made up of melanoma cells (MLANA, PMEL, MITF, DCT), endothelial cells (VWF, PECAM1) and fibroblast cells (COL1A1, COL3A1)." (PMID 36433984, 2022). "However, 17-AAG, in combination with and without PLX4032, increased the expression of DCT and TYRP1, but not TYR, in all 3/3 BRAFWT melanoma cell lines." (PMID 29481571, 2018).